FEN1 (flap structure-specific endonuclease 1)
Diseases named in the same sentence as FEN1 in open-access papers (continued):
Sharing a sentence is not in itself a finding about the gene and the disease.
cancer (continued). "Due to its pivotal role in DNA repair, dysregulated FEN1 results in deficient DNA repair and subsequent accumulated mutations and predisposition to cancer, as evident in preclinical studies." (PMID 34809722, 2021). "According to the Cancer Genome Atlas (TCGA) database, overexpression of FEN1 has been associated with several types of cancers including gastric, breast, prostate, lung, pancreatic, and brain cancer." (PMID 34809722, 2021). "Two FEN1 single nucleotide polymorphisms (69G>A and 4150G>T) were associated with high risk in various cancers." (PMID 34277392, 2021). "Our current work thus provides an important cue to develop a therapeutic strategy for cancers with FEN1, POL δ and LIG1 mutations in which Okazaki fragment joining is strongly suppressed upon treatment with PARP and HDAC inhibitors." (PMID 33872376, 2021). "Because of its essential roles, deficiencies in FEN1 function or deletion of the FEN1 gene would result in predisposition to cancer and rapid tumor development." (PMID 34277392, 2021). "In this respect, FEN1 deficiency can induce mutations, chromosomal instability, and mini- and micro-satellite instability, thereby predisposing to cancer development." (PMID 33339161, 2020). "The down-regulation of the FEN1 gene has been implicated in causing genomic instability and cancer predisposition." (PMID 33383666, 2020). "Overall, FEN1 overexpression as well as loss of function have been associated with human cancers, likely related to the dual nature of FEN1, being involved in DNA replication and in DNA repair." (PMID 32547565, 2020). "Knock-in of a cancer-related inactivating Fen1 mutation resulted in a high incidence of lung carcinomas." (PMID 32547565, 2020). "FEN1 is essential for the maintenance of genome stability and is associated with the onset and progression of various cancers including lung, breast, gastric, prostate and pancreatic cancer." (PMID 31402791, 2019). "Emerging evidence has shown that FEN1 dysfunction leads to genomic instability and increased cancer susceptibility." (PMID 31402791, 2019). "Regulation of FEN1 activity is important in maintaining genome stability as overexpression of FEN1 is associated with poor prognosis in various cancers." (PMID 30558228, 2018). "FEN1 promotes cell proliferation, and its deficiency or overexpression can result in predisposition to cancer and the rapid development of tumors." (PMID 29541412, 2018). "In this study, we found that FEN1 overexpression is associated with cancer progression, while it is inversely correlated with survivorship in non‐small‐cell lung cancer." (PMID 28371273, 2017). "We identify synthetic genetic interactions between these inhibitors and disruption of DNA damage repair genes, and our data suggests FEN1 as a potential target for drug discovery in DNA repair-deficient cancers." (PMID 28628639, 2017). "So, although tumour mutation data has been called ‘a bewildering hodgepodge of genetic oddities’58, for FEN1, there is a clear link of structurally-mapped mutations to compromised function, genomic instability and cancer." (PMID 28653660, 2017). "FEN1 mutations that specifically disrupt the PCNA interaction have been reported to cause aneuploidy‐associated cancer progression." (PMID 28371273, 2017). "In the same vein a defective DNA repair caused by a deficiency of the Fen1 exonuclease resulted in cancer initiation and a chronic inflammation promoting cancer progression." (PMID 27555866, 2016). "Mutations which reduce FEN1 activity have also been demonstrated to vastly increase cancer incidence in mouse models." (PMID 26545110, 2015). "FEN-1 defects are associated with genomic instability and subsequent development of cancer and other diseases in eukaryotes." (PMID 24701133, 2014). "FEN1 is significantly up-regulated in multiple human cancers and its aberrant expression in tumor cells is associated with hypomethylation of the CpG islands within the FEN1 promoter." (PMID 24748173, 2014).
cancer (continued). "Defects in FEN1 cause accumulation of mutations, genomic instability, cancer predisposition and chronic inflammation." (PMID 24349332, 2013). "It has been shown that defects in the gap-dependent endonuclease and exonuclease of FEN1 cause chronic inflammation and cancers." (PMID 24349332, 2013). "We identified small-molecule inhibitors of one such target, FEN1, and showed that these compounds were able to selectively kill human cells carrying cancer-relevant mutations." (PMID 23382697, 2013). "We performed mutation signature analysis, to define whether defective FEN1 methylation (R192Q) or defective FEN1 demethylation (Jmjd1b−/−) causes a unique mutation signature and whether their mutation signatures correspond to those identified in human cancers." (PMID 41280084, 2025). "The enhanced expression of FEN1 could be linked to the accelerated proliferation rate in cancer cells and be required for BER in the case of DNA damage." (PMID 38396787, 2024). "The dysregulation of the FEN1 gene and miR-4324 has been associated with cancer progression." (PMID 35246224, 2022). "Further analysis of clinical samples also found that high expression of FEN1 was associated with aggressive tumor behavior and may directly play a role in the progression of carcinoma in situ to aggressive disease." (PMID 35883563, 2022). "The important roles of FEN1 in maintaining genome stability and integrity have been further demonstrated by the fact that the insufficiency of FEN1 is associated with lung and gastrointestinal cancers and induces various mutations and genome instability in cancers." (PMID 36672839, 2022). "Furthermore, localization, protein-protein interactions, post-translational modifications and other regulatory mechanisms of FEN1, as well asFEN1 mutations and correlation with cancer were summarized." (PMID 33827468, 2021). "Polymorphic variants of FEN1 may be associated with increased cancer susceptibility in human studies." (PMID 33919707, 2021). "For instance, null mutation of FEN1 in mouse model harboring heterozygous mutation resulted in cancer predisposition including lymphoma and contributed to gastrointestinal cancer when combined with heterozygous mutation in adenomatous polyposis coli (APC) gene." (PMID 34809722, 2021). "FEN1 E160D mutant mouse model displayed increased mutation frequency and cancer development." (PMID 33919707, 2021). "The level of FEN1 is inversely associated with cancer drug and radiation resistance." (PMID 31777591, 2019). "Mutations in FEN1 that disrupt its interaction with PCNA also induce aneuploidy-associated cancer." (PMID 31402791, 2019). "When FEN1 is overexpressed, the highly inaccurate DNA repair pathway may be favored, causing a great risk of potential mutation and increased risk of cancer." (PMID 30011902, 2018). "Once the coding region of FEN1 is changed, the genetic abnormality can lead to an abnormal increase or decrease of FEN1 content in the body, and functional deficiency of FEN1 can cause genomic instability and predisposition to cancer." (PMID 29541412, 2018). "Functional deficiency in FEN1 has been shown to cause genomic instability, chronic inflammation and cancer; thus may be a potential candidate cancer susceptibility gene." (PMID 29348864, 2017). "The data above have already indicated that FEN1 overexpression was associated with cancer." (PMID 28371273, 2017). "Based on these reports, we speculate that FEN1 could be used as a promising cancer diagnostic biomarker." (PMID 28371273, 2017). "Haploinsufficiency of FEN1 is associated with abnormal cell-cycle progression and cancer predisposition with decreased survival, driven by an accumulation of replication-associated alterations in DNA, such as microsatellite instabilities (MSI) and tri-nucleotide repeat expansion." (PMID 28628639, 2017). "Interestingly, the rs174538 polymorphism is significantly associated not only with cancer risk but also with FEN1 mRNA levels in normal tissues." (PMID 27801669, 2016).
cancer (continued). "Previous studies have suggested that single nucleotide polymorphisms (SNPs) in FEN1 may confer susceptibility to cancer." (PMID 27801669, 2016). "FEN1 is expressed in many species, from archaebacteria to humans, and FEN1 functional deficiency may lead to genomic instability and cancer development." (PMID 26668074, 2015). "Naturally occurring genetic variations in FEN1 expression or function may also contribute to cancer susceptibility." (PMID 26668074, 2015). "Screening of human cancers for FEN-1 mutations revealed that defects could be identified that affect 5′ exonuclease activity and GEN activity." (PMID 24701133, 2014). "Given that the majority of the genetic interactions were conserved in the CIN synthetic lethal interaction network interrogated here, FEN1 may be a widely applicable target in cancers harboring mutations in a variety of CIN genes." (PMID 23382697, 2013). "Yeast RAD27 is a CIN gene, and FEN1 mutation in various systems leads to CIN and has been associated with cancer; thus, inhibition of FEN1 in cancers that already exhibit CIN could lead to a level of CIN incompatible with viability." (PMID 23382697, 2013). "Moreover, functional defects in FEN1 were linked to increased risk in human cancer types." (PMID 32547565, 2020). "However, several somatic FEN1 mutations have been detected in human cancer (GDC) but the relationship between FEN1 deficiency and cancer susceptibility remains unclear." (PMID 31518347, 2019). "Suppression of FEN1 leads to the retardation of DNA replication and accumulation of unrepaired DNA intermediates, resulting in DNA double strand breaks (DSBs) and apoptosis this may leads to cancer, DNA repair alters the risk of cancer." (PMID 28187440, 2017). "FEN1(Flap endonuclease 1) is a central component in cellular metabolism, over expression and decrease of FEN1 levels may cause cancer, these regulation changes of Flap endonuclease 1reported in many cancer cells, to consider this data may needs to develop a network based biomarker." (PMID 28187440, 2017). "However, the underlying mechanisms that up-regulates FEN1 upon drug treatment and confers the drug resistance to cancer cells remain unclear." (PMID 25885449, 2015). "To explore the origination of SVs, we have analyzed 1,340 cancer genomes with annotation of 4,608 novel small inverted triplication (SIT) events and found that FEN1 is strongly associated with SIT incidence." (PMID 41945861, 2026). "Promisingly, FEN1 small molecule inhibitors have been developed that show anti-cancer effects in experimental models." (PMID 40447568, 2025). "FEN1 plays a pivotal role in regulating NB cell proliferation, invasion, and migration, thereby facilitating cancer progression." (PMID 40612863, 2025). "Several recent studies have found that FEN1 is highly expressed in a variety of cancers and is positively correlated with tumor proliferation rate, tumor size, lymph node metastasis, and degree of differentiation." (PMID 39759116, 2025). "FEN1 has been proposed as an anti-cancer drug target because of its synthetic lethal interaction with homologous recombination deficiency (HRD)." (PMID 41359388, 2025). "FEN1 has been found to be pivotal for drug resistance and proliferation in several types of cancer, because it repairs damaged DNA after chemotherapy." (PMID 40001488, 2025). "FEN1 has already been described as a potential target structure for inhibitor-based therapy of cancer cells, particularly those with defects in homologous recombination." (PMID 38396787, 2024). "Flap structure-specific endonuclease 1 (FEN1) is highly expressed in various cancer cells and plays an important role in DNA replication and repair." (PMID 39464890, 2024). "Previous studies have shown that FEN1 is abnormally expressed in lung, breast, gastric, prostate and other types of cancer and is closely correlated with the occurrence and development of tumors 10-12." (PMID 38230217, 2024).
cancer (continued). "The expression of Fen1 in many cancer types is very high, supporting the hyper-proliferation of cancer cells." (PMID 38178179, 2024). "Four key genes CCL2, CCR7, LY96, and PTPRC, from ClusterK1 and five genes AURKA, CDK1, CCNA2, FEN1, and PLK1 from ClusterK2, were associated with at least one type of cancer." (PMID 38872418, 2024). "Enhanced FEN1 expression in cancer cells improves DNA repair processes and can lead to the development of drug resistance." (PMID 38396787, 2024). "After proving specific interaction between hnRNPA1 and FEN1 rG4, the correlations between the expression of FEN1 and hnRNPA1 in different types of cancer tissues were analyzed by the GEPIA database." (PMID 36829835, 2023). "In cancers with deficient BRCA1/2 proteins, FEN1 inhibition has been shown to increase sensitivity to DNA damage leading to cell death." (PMID 37508568, 2023). "The authors designed a DNA nanosphere system to specifically sense cancer biomarker flap endonuclease 1 (FEN1) and spatiotemporally modulate drug release." (PMID 37110795, 2023). "Since FEN1 is also required for DNA replication, the efficacy of these inhibitors in cancer cell killing targeting BER mechanisms needs to be elucidated." (PMID 37762489, 2023). "To confirm this result, we examined the mRNA and protein levels of FEN1 in other cancer cells with the same treatment." (PMID 36829835, 2023). "They propose that the development of efficacious small-molecule inhibitors targeting FEN1 would be an excellent strategy to treat various cancers." (PMID 37298600, 2023). "In this context, miR-140 has been described to play tumor suppressor functions through downregulation of Flap Endonuclease 1 (FEN1), which is involved in DNA repair and cancer progression." (PMID 34524579, 2022). "In conclusion, the aberrant expression of FEN1 in a variety of tumors makes it an effective target and prognostic biomarker for cancer therapy." (PMID 35883563, 2022). "Increasing evidence suggests that FEN1 promotes cancer development by promoting cell proliferation, migration, and invasion and decreasing apoptosis." (PMID 35246224, 2022). "This outcome suggests that FEN1 is a critical component for promoting cancer cell survival and rapid proliferation during the replication stress response." (PMID 35414100, 2022). "Dozens of inhibitors targeting FEN1 through high-throughput screening were filtered, which had more or less of an effect on the treatment of cancer." (PMID 35883563, 2022). "The development of small-molecule inhibitors targeting FEN1 is a good strategy for treating cancers." (PMID 35883563, 2022). "Overexpression of FEN1 is observed in many cancer types and is correlated with cancer aggressiveness." (PMID 36077176, 2022). "The subpopulations of FEN1-upregulated cancer cells bearing selective advantages survived at the expense of the tumor evolution process and strengthens the case that homologous recombination is an important target for clinical intervention." (PMID 35414100, 2022). "Although FEN1 was the only one endonuclease included in the present study, its potential role in cancer development was fully demonstrated by a heterozygous animal model." (PMID 33391423, 2021). "Substantial research has been undertaken regarding the role of FEN1 in the onset and progression of different cancers." (PMID 34277392, 2021). "FEN1 was detected in culture medium of BC cell lines and serum FEN1 concentrations were significantly increased in BC patients than in cancer-free individuals." (PMID 34277392, 2021). "FEN1 participates in various DNA metabolism pathways and contributes to cancer progression and drug resistance." (PMID 34277392, 2021). "A double heterozygous mouse model with a mutation in FEN1 and adenomatous polyposis coli (APC) gene showed enhanced cancer development and poor survival." (PMID 33919707, 2021).
cancer (continued). "Based on the findings of FEN1 expression in pan-cancer, we further evaluated FEN1 mRNA expression in HCC and peritumoral tissues using TCGA and GEO HCC database." (PMID 32399086, 2020). "Many studies have shown that FEN1 is highly expressed in proliferative cancer cells and is essential for cell growth in tumor tissues." (PMID 32318339, 2020). "Mutations in genes required for Okazaki fragment processing such as FEN1 also sensitize cells to PARP inhibition, but FEN1 is rarely mutated in cancer." (PMID 32029455, 2020). "The evidence presented here reveals that the synthetic lethal interaction between miR-1193 inhibition and DNA-PKcs deficiency significantly suppresses cell growth and promotes apoptosis through the YY1AP1/YY1/FEN1 pathway in M059J cancer cells." (PMID 32732911, 2020). "A higher level of FEN1 expression was detected in rapidly dividing cells, including various types of cancer cells, than in cells with normal division kinetics and is associated with enhanced malignancy and decreased survival rates." (PMID 32732911, 2020). "Over expression of FEN1 has been found in many cancers and it can influence the cell proliferation and differentiation." (PMID 32340320, 2020). "Studies have shown that FEN1 has a dual function in DNA replication and repair, and its expression levels and functional disorder can induce genomic instability, leading to cancer development." (PMID 32399086, 2020). "Previous reports have shown that FEN1 is highly expressed in several types of cancer, and significantly reduces the efficacy of anti-tumor drugs." (PMID 32318339, 2020). "This is in agreement with previous studies showing that FEN1 promotes cancer development and is required for S-phase entry in trophoblasts." (PMID 31402791, 2019). "Previous studies confirmed that FEN1 not only promoted cancer cell proliferation and progression but also conferred cancer drug resistance." (PMID 30774662, 2019). "FEN1 is overexpressed in many forms of cancer and has been reported as a potential biomarker and target in different types of cancer." (PMID 31670906, 2019). "The ONCOMINE and FIREBROWSE databases were further utilized to investigate the expression of FEN1 in various cancers, including HCC." (PMID 31534853, 2019). "The IHC score of FEN1 in HCC tissue was significantly higher than that in the tissue adjacent to the carcinoma." (PMID 31402791, 2019). "FEN1 is an enzyme involved in DNA damage repair, which was found to be overexpressed in the majority of cancers." (PMID 30011902, 2018). "As such, human FEN1 (hFEN1) has been postulated to be a potential cancer therapeutic target, and evidence suggests that combinatorial targeting of hFEN1 has therapeutic relevance." (PMID 29718417, 2018). "In humans, cancer cells overexpress FEN1, and tumor aggressiveness correlates with FEN1 protein levels." (PMID 29718417, 2018). "The dual function of FEN1 in DNA replication and repair makes it an ideal target for cancer therapy." (PMID 28371273, 2017). "Multiple DEGs, including FEN1, BCAT1, AGPS and CCL3, have been implicated in the progression of various cancers." (PMID 29033691, 2017). "This process is critical for proficient and processive replication, with many cancer cells showing over-expression of FEN1." (PMID 28628639, 2017). "DNA replication and repair enzyme Flap Endonuclease 1 (FEN1) is vital for genome integrity, and FEN1 mutations arise in multiple cancers." (PMID 28653660, 2017). "For these reasons, the inhibition of FEN1 has more severe impacts on cancer cells than on the surrounding normal tissues." (PMID 28371273, 2017). "Inhibiting FEN1 in cancer cells not only suppressed cancer progression but also enhanced the toxicity of DNA damage‐inducing agents." (PMID 28371273, 2017). "This sensitivity is due to a synthetic lethal interaction between FEN1 and MRE11A, which is often mutated in MSI cancers through instabilities at a poly(T) microsatellite repeat." (PMID 28628639, 2017).